CD44 (CD44 molecule (IN blood group))
Diseases named in the same sentence as CD44 in open-access papers (continued):
Sharing a sentence is not in itself a finding about the gene and the disease.
gastric cancer (continued). "Kaplan-Meier analysis revealed that high CD44 mRNA was correlated with a benign survival rate in gastric cancer (P = 0.011), while the opposite role of CD44 mRNA was observed in colon cancer (P = 0.005)." (PMID 27323782, 2016). "Second, the high CD44 mRNA level was found in colon and gastric cancer, and it correlated with a benign survival rate in gastric cancer." (PMID 27323782, 2016). "Our findings indicate that SALL4 promotes gastric cancer growth and metastasis through the activation of CD44, which represents a new mechanism responsible for the oncogenic roles of SALL4 in cancer." (PMID 27819668, 2016). "Stable or inducible knockdown of SALL4 suppressed gastric cancer cell proliferation, migration and invasion, while CD44 overexpression antagonized these inhibitory effects." (PMID 27819668, 2016). "We next performed the rescue study to determine the importance of CD44 regulation to the oncogenic roles of SALL4 in gastric cancer." (PMID 27819668, 2016). "CD44, widely accepted as a CSCs marker for gastric cancer in many studies, is involved in cell-cell adhesion, cell-matrix interactions, and tumour metastasis." (PMID 26839535, 2016). "We also found a positive correlation between SALL4 and CD44 expression in gastric cancer cell lines and gastric cancer tissues, further supporting the regulation of CD44 by SALL4." (PMID 27819668, 2016). "CD44 expression was positively correlated with lymph node and distant metastasis, and poorer outcome of gastric cancer patients." (PMID 27323782, 2016). "In this study, first, we found that low alteration frequency of CD44 mRNA in colon and gastric cancer." (PMID 27323782, 2016). "The results of rescue study revealed that CD44 overexpression antagonized SALL4 knockdown-mediated inhibition of gastric cancer cell proliferation, migration, and invasion in vitro and gastric cancer growth in vivo." (PMID 27819668, 2016). "In this study, we evaluated the significance of CD44 mRNA in human colon and gastric cancer by using The Cancer Genome Atlas (TCGA) data portal." (PMID 27323782, 2016). "Herein, we found that miR-501-5p increased the stemness in gastric cancer by activating the Wnt/β-catenin signaling and increasing the expression of CD44 and c-Myc." (PMID 27846906, 2016). "The more precise mechanisms by which CD44 maintains the stemness of gastric cancers and how the CD44-p-ERK-Oct4 positive feedback loop functions warrants further studies." (PMID 26769843, 2016). "Taken together, these results suggest that SALL4 regulates the expression of CD44 in gastric cancer cells through binding to its promoter." (PMID 27819668, 2016). "There are very few studies in the literature evaluating the interaction between the Shh pathway and CD44 in gastric cancer cells." (PMID 26839535, 2016). "In this study we demonstrated that SALL4, a stem cell factor, promoted gastric cancer progression by activating CD44 expression." (PMID 27819668, 2016). "Using Kaplan-Meier analysis and the log-rank test, we find that gastric cancer patients with CD44-positive staining had poorer overall survival." (PMID 26839535, 2016). "We next investigated the role of CD44 in cancer progression using a well-establishedMongolian gerbil model of gastric cancer." (PMID 25658601, 2015). "Expression of CD47 and CD44, a known gastric cancer stem cell marker, were investigated in gastric cancer cell lines by flow cytometry." (PMID 26077800, 2015). "Hedgehog signaling pathway has been shown to be important in the maintenance of chemotherapy resistance in a subgroup of CD44+ gastric cancer cells." (PMID 25823654, 2015). "Actually, CD44 is widely known as a CSCs marker, not only in liver cancer but also in gastric cancer, breast cancer, acute myeloid leukemia." (PMID 26540347, 2015). "To date, drugs targeting CD47, CD44 and c-met have been developed to treat breast, lung, colon and gastric cancer and leukemia." (PMID 25658794, 2015).
gastric cancer (continued). "We performed xenograft transplantations of FACS-sorted gastric cancer cells according to the CD44 and CD47 expression levels of the MKN45 and MKN74 cancer cell lines into the subcutaneous space of SCID mice." (PMID 26077800, 2015). "We evaluated the proliferation of gastric cancer cells according to the expression levels of CD44 and CD47, that is, CD44hi or CD44lo and CD47hi or CD47lo." (PMID 26077800, 2015). "Collectively, thesedata show that CD44 signaling mediates H. pylori-induced atrophic gastritis and hyperproliferation in theMongolian gerbil model of gastric cancer." (PMID 25658601, 2015). "In clinical settings, CD44 expression has been reported to be an unfavorable prognostic factor in gastric cancer patients 5,39." (PMID 26077800, 2015). "Flow cytometric analyses revealed that the MKN45 and MKN74 gastric cancer cell lines expressed both CD44 and CD47 on ∼90% of the tumor cells." (PMID 26077800, 2015). "CD44–HA signaling was also shown to be important in the progression toward gastric cancer after a complication of H. pylori infection." (PMID 25954275, 2015). "In severe combined immunodeficiency mice, CD44-positive gastric cancer cells are highly tumorigenic and resistant to chemotherapeutics or radiation." (PMID 25669984, 2015). "This defense mechanism against oxidative stress partly accounts for the enhanced tumorigenicity and chemoradioresistance of CD44-positive gastric cancer cells." (PMID 26077800, 2015). "MKN45 and MKN74 gastric cancer cells were sorted by fluorescence-activated cell sorting according to CD44 and CD47 expression levels, and their in vitro proliferation, spheroid-forming capacity, and in vivo tumorigenicity were studied." (PMID 26077800, 2015). "The high expression of CD44 is positively correlated with malignant transformation, metastasis, and relapse of gastric cancer." (PMID 25945346, 2015). "Obviously, the expression of CD44 on hybrid cells was stronger than the parental gastric cancer cells." (PMID 26498753, 2015). "A recent study shows that microRNA-106b is upregulated only in CD44+ gastric cancer cells undergoing EMT and that TGF-β signaling was also elevated." (PMID 25954275, 2015). "In the well-established Mongolian gerbil model of gastric cancer, animals treated with CD44 peptide inhibitor Pep1,resulted in the inhibition of H. pylori-inducedproliferation and associated atrophic gastritis." (PMID 25658601, 2015). "MMP7 and CD44, both β-catenin downstream genes, were involved in macrophage-activated gastric cancer cell invasion." (PMID 26226629, 2015). "CD44+ cells have been found in breast and gastric cancer in spite of a relatively small fraction in tumor cell populations." (PMID 25658794, 2015). "CD44 is also a known downstream target of Wnt/β-catenin pathway and expressed in a variety of solid tumors including gastric cancer." (PMID 25669984, 2015). "We found that the long-term trastuzumab treatment induced CSC-like properties in gastric cancer cells, including elevated expression of CD44, CD133, and OCT4, self-renewal (forming mammospheres), higher clonogenicity, and increased tumorigeniticy." (PMID 25669984, 2015). "Several previous studies demonstrated that CD44-positive gastric cancer cells possessed the features of CSC." (PMID 25669984, 2015). "CD24 and CD44 expression levels were significantly higher in patients with gastric cancer compared with those in paired controls (45.5% vs. 0.0%, and 61.0% vs. 0.0%, P < 0.001)." (PMID 25212506, 2014). "The mRNA expression levels of CD24 and CD44 were consistent with the immunohistochemistry results in gastric cancer." (PMID 25212506, 2014). "The aim of this study was therefore to evaluate the expression levels of CD24 and CD44 in gastric cancer and to evaluate their possible predictive relevance for future clinical practice." (PMID 25212506, 2014).
gastric cancer (continued). "They reported that CD44(+) gastric cancer cells showed the stem cell characteristics of self-renewal and the ability to form differentiated progeny and give rise to CD44(−) cells." (PMID 25212506, 2014). "CD44 is a transmembrane glycoprotein that is well known as a cancer stem cell marker in gastric cancer." (PMID 25441488, 2014). "In our study, the expression of CD44 in intestinal type gastric cancer was significantly higher than the diffuse type and it was interestingly associated with the tumor size (4-8 cm), depth (serous involvement) and grade (moderately differentiated)." (PMID 25635255, 2014). "The present study determined that the combination of alterations in the protein expression of vimentin, E-cadherin, and CD44 was the most effective prognostic factor in gastric cancer." (PMID 25441488, 2014). "We confirmed that SP cells utilized in this study express candidate gastric cancer stem cell markers including CD44, CD133, and NANOG." (PMID 25379943, 2014). "Among 77 paired samples, CD24(+) and CD44(+) staining results were found in 35/77 (45.5%) and 47/77 (61.0%) of the gastric cancer samples, respectively." (PMID 25212506, 2014). "We show that in addition to CD44/SLC1A2 in gastric cancer, SLC1A2 is involved in a novel but analogous gene fusion, APIP/SLC1A2, in colon cancer." (PMID 23637631, 2013). "Here, we report that CD44+ gastric cancer stem-like cells (GCSCs) showed enhanced proliferation capacity compared to their CD44− counterparts, and this proliferation was accompanied by the high expression of Notch-1 (in vitro)." (PMID 23710217, 2013). "This small retrospective series served as an initial study to investigate the potential association between CD44 and CD24 and gastric cancer recurrence, but a study with a larger sample is needed to confirm our preliminary results." (PMID 22839505, 2012). "For example, CD44 has been demonstrated to be more specific than CD133 for isolating gastric cancer-initiating cells from a panel of human gastric cancer cell lines." (PMID 22558209, 2012). "Subsequently, we used the same method to analyze the copy number of ERBB4, C-MET and CD44 genes in the 128 gastric cancers and 37 normal controls." (PMID 22606006, 2012). "A retrospective study of 100 patients with gastric cancer evaluated the expression of CD44 and its prognostic importance, concluding that this cell adhesion molecule is highly expressed in gastric adenocarcinoma." (PMID 22839505, 2012). "Aberrant expression and presence of multiple high molecular weight isoforms of CD44 that are generated by alternate splicing are frequently encountered in breast, colon and gastric cancers." (PMID 22937154, 2012). "The purpose of this study was to evaluate the correlation of CD44/CD24 expression with recurrent gastric cancer and to determine its prognostic significance." (PMID 22839505, 2012). "Amplification of ERBB4, C-MET and CD44 significantly affected the poor survival of gastric cancer patients." (PMID 22606006, 2012). "In SCID (severe combined immunodeficiency) mice, CD44 positive gastric cancer cells are able to induce tumor, knockdown CD44 by short hairpin RNA decreases the tumorigenicity." (PMID 23217022, 2012). "In addition, PAK1 has been reported to regulate the alternative splicing of CD44 by phosphorylating PCBP115 or promote the expression of CD44 through the PAK1/ATF2/miR-132 cascade in gastric cancer." (PMID 41459112, 2026). "Therefore, we next investigated the CD44v9 expression in the gastric cancer tissue array (BS01011b) using C44Mab-1-mG2a and an anti-pan CD44 mAb, C44Mab-46-mG2a." (PMID 41009730, 2025). "Furthermore, a comprehensive multi-omic analysis of malignant gastric cancers revealed genomic amplifications of established cancer driver genes such as EGFR, ERBB2, MET, FGFR2, and CD44 in gastric cancer with peritoneal metastasis." (PMID 41009730, 2025).
gastric cancer (continued). "Furthermore, most NINJ2+ cells in the ECF-R gastric cancer cells also highly expressed CD44, and most of the NINJ2− cells were also CD44− cells." (PMID 40518514, 2025). "The cell-surface adhesion molecule CD44 has been identified as a marker of gastric cancer stemness and may play a role in cancer development, particularly when exacerbated by Helicobater pylori infection." (PMID 40864800, 2025). "Interestingly, in a recent study, using the same reagents and scoring system, Al-Janaby and colleagues examined the co-expression of HER family members and CD44 in 78 patients with stomach cancer." (PMID 40227788, 2025). "In addition, there was facilitated or reduced ELAVL1 enrichment on CD44 pre-mRNA in gastric cancer cells with stable over-expression or knockdown of CMTR1, while silencing or ectopic expression of SNORA37 abolished these effects." (PMID 39815331, 2025). "Based on over-lapping analysis of top 60 changes in alternative splicing events (|ΔPSI|≥ 50%, P < 0.05) in MKN-45 cells over-expressing SNORA37 and gastric cancer tissues, only CD44 and PRMT2 were found to exhibit consistent alternative splicing events and selected for further analysis." (PMID 39815331, 2025). "NINJ2-expressing ECF-R cells highly expressed CD44, which is a gastric cancer stem cell marker." (PMID 40518514, 2025). "Galectin-4 further contributes to peritoneal metastasis through interactions with specific membrane proteins such as mesenchymal–epithelial transition factor (c-MET) and CD44, both of which are known to be involved in gastric cancer progression and epithelial-to-mesenchymal transition." (PMID 40710343, 2025). "Furthermore, IHC analysis indicated a notable increase in CD44 expression in gastric cancer tissues relative to adjacent normal tissues, underscoring the potential role of CD44 in promoting tumor progression." (PMID 40069421, 2025). "Activation of CD44 or Nrf2 regulates stem cell traits in several cancers, including gastric cancer." (PMID 40864800, 2025). "Correlation analysis of CD44 and gastric cancer progression." (PMID 40069421, 2025). "Furthermore, CD44+ gastric cancer cells also displayed enhanced resistance to chemotherapy and radiation-induced cell death." (PMID 38612911, 2024). "A previous study revealed that CD44, a stem cell marker in gastric cancer (GC) lines, could be suppressed by DAXX." (PMID 38783892, 2024). "Moreover, flow cytometry analysis revealed that the knockdown of RPRD1A in gastric cancer cell lines resulted in marked elevated proportion of CD44+ cells." (PMID 38714724, 2024). "Furthermore, a cell fluorescence recovery assay revealed that transfection with Circ-0075305 or miR-708-5p mimic led to changes in the gastric cancer stem cell-related markers CD44 and NANOG; however, these effects were reversed by sh-RPRD1A." (PMID 38714724, 2024). "We showed that SRGN knockdown or CD44 inhibition decreases IL-8 production in gastric cancer cells." (PMID 38862740, 2024). "Additionally, these CD44+ gastric cancer cells exhibited increased resistance to radiation and chemotherapy-induced cell death." (PMID 39840036, 2024). "CD44 (a cell surface transmembrane glycoprotein) and ABCG2 (adenosine triphosphatase binding cassette transporter G superfamily member) are primarily implicated in the prognosis of gastric cancer." (PMID 38882596, 2024). "The downstream WNT target CD44 has demonstrated prognostic significance in gastric cancer (GC)." (PMID 38987552, 2024). "Elevated Lgr5 expression, especially in conjunction with other early gastric cancer markers such as CD44 and CD133, has been postulated to be predictive of a particularly high risk of progression to an advanced stage of disease, i.e., low-grade dysplasia or later." (PMID 39191487, 2024). "Moreover, CD44 was reported to have its glycosylation profile affected in gastric cancer alongside other intestinal cancers." (PMID 39767693, 2024).
gastric cancer (continued). "In gastric cancer stem cells, CD44 is overexpressed while CD24 is under expressed." (PMID 39247186, 2024). "Moreover, CD44+ gastric cancer cells display similar stem cell properties of self-renewal and are able to give rise to CD44+ cells in vitro and in vivo." (PMID 39840036, 2024). "In addition, DR5 was also correlated with TMB, MSI, expression of Ki67 and CD44, and tumor stemness in gastric cancer, which need further deep research." (PMID 37879960, 2023). "The positive reciprocal regulation of FGFR2 and CD44 was found to be important in gastric cancers." (PMID 37443779, 2023). "Furthermore, we found a correlation between high-risk gastric cancer and extracellular matrix (ECM) receptor interaction, high infiltration of macrophages, CD44, and HLA-DOA." (PMID 36968601, 2023). "Moreover, it was found that effective vitamin D [(1,25(OH)2D3)] significantly hindered the growth of CD44-expressing human gastric cancer cells." (PMID 38274206, 2023). "CD44 is also a marker molecule for many tumor–stem cells, including gastric cancer." (PMID 36918410, 2023). "Since rapamycin, which down-regulates HIF-1α, could revert these changes, HIF-1α was suggested as the mediator of CD44 induction and stemness in gastric cancer cells." (PMID 36846589, 2023). "These CD44+ gastric cancer cells are invasive and resistant to chemotherapy." (PMID 36838713, 2023). "Cancer stem cells of gastric cancer expressed high levels of CD44." (PMID 37190178, 2023). "O-glycan truncation in gastric cancer can enhance cancer-related functions of CD44." (PMID 36873741, 2023). "Gastric cancer cells expressing CD44 showed enhanced self-renewal capacity and, interestingly, could give rise to a subpopulation of CD44-cells." (PMID 36768445, 2023). "By analyzing the co-expression correlation between CPT1A, IL-8, CXCL5, STC1 and CD44 in stomach cancer tissues through TCGA database, we found that these genes except CXCL5 were positively correlated with CD44 and were positively associated with at least one MSC markers (ENG, THY1, NT5E)." (PMID 37158903, 2023). "Similarly, our study found that m6A levels were altered in both malignantly transformed gastric epithelial cells and gastric cancer tissues, and CD44 was positively correlated with the expression level of FTO." (PMID 36918410, 2023). "Low differentiation of tumor and poor prognosis of gastric cancer correlate with CD44." (PMID 36918410, 2023). "The specific mechanisms by which zyxin regulates the expression of gastric cancer cell stemness marker CD44 remain unknown." (PMID 37667739, 2023). "Direct or indirect downregulation of CD44 expression can inhibit the proliferation, invasion and metastasis of gastric cancer, suggesting that CD44 may be a valuable therapeutic target for gastric cancer." (PMID 36316684, 2022). "Cell surface proteins are used as CSC markers for different types of tumors, for example, cluster of differentiation 34-positive (CD34+)/CD38 − for leukemia cells, CD13/CD45/CD90 for liver cancer, CD117/CD90/epithelial cell adhesion molecule for lung cancer, and CD44 for colon and gastric cancers." (PMID 35148781, 2022). "CD44 is highly expressed in gastric cancer compared with normal tissues." (PMID 36316684, 2022). "TGFβ2 was negatively correlated with mRNAsi and significantly positively correlated with stemness markers (DCLK1 and CD44) in this study, so TGFβ2 may be important factor in maintaining tumor stemness and promoting tumor differentiation in gastric cancer." (PMID 35620459, 2022). "Furthermore, a recent study using the Mongolian gerbil model found that CD44 genes are crucial in the proliferation of epithelial cells and gastric cancer development in response to H. pylori infection." (PMID 35683528, 2022). "Therefore, we selected CD44 as a biomarker to establish a drug-resistant stem cell model of gastric cancer for further research." (PMID 35941687, 2022). "miR-34a influences the survival prognosis of gastric cancer patients by regulating CD44." (PMID 36316684, 2022).